MX1 (MX dynamin like GTPase 1)
Diseases named in the same sentence as MX1 in open-access papers (continued):
Sharing a sentence is not in itself a finding about the gene and the disease.
viral infection (continued). "Here we hypothesized, that if Mx1 would be expressed constitutively and ubiquitously in all porcine cells, animals would be armed to promptly combat and thus resist viral infections." (PMID 25408889, 2014). "In this study we tested the hypothesis that Mx1 could be used to generate pigs that resist viral infection." (PMID 25408889, 2014). "Finally, the overexpression of MX1, a well-characterized biomarker of viral infection; IFIT1, one of the top upregulated genes; and OAS1, OAS2 and OAS3, genes with a molecular function, 2-5-oligoadenylate synthase activity, identified as enriched in the DGE analyses, was confirmed by RT-qPCR." (PMID 42194954, 2026). "For the cell lines analyzed here, we could demonstrate that major aspects of the IFN system, including sensing of virus and induction of ISG expression, are intact, as evidenced by strong IFN beta induction upon VSV infection and strong induction of the ISG MX1 upon IFN treatment or viral infection." (PMID 38743751, 2024). "Finally, the P. alecto type I IFN locus mediates constitutive expression of IFN-alpha along with expression of IFN-stimulated genes such as tetherin and Mx1 genes, suggesting that bat cells may be intrinsically armed to defend against viral infections." (PMID 32934084, 2020). "Thus, the association of IRF-1, IFI-44, Mx1, OAS2, and HSH2D with HLA-DR could suggest a possible relationship between viral infection and HLA-DR expression." (PMID 30374345, 2018). "The P protein was shown to specifically target the interferon-beta (Ifn-β), myxovirus resistance protein 1 (Mx1) and 2′-5′-oligoadenylate synthetase 1 (Oas1) genes, resulting in the decreased expression of these genes that are important in innate responses against viral infections." (PMID 27548204, 2016). "The highest ratio in this set was two-fold and out of the top 10 specificities, 7 were in the Type I interferon signature (IFITM3, MX1, IFI6, IFI44L, ISG15, OAS1, IFIT3) and one encodes a protein that is activated by dsRNA as might be present in a viral infection (EIF2AK2)." (PMID 21366908, 2011). "The sGenes found within this gene set include MX1, HLA-C, and IFI44, which play important roles in host response specifically to viral infections." (PMID 41542048, 2026). "Previous literature has shown that type I interferon activation stimulates the upregulation of antiviral gene MX1 following CVB3 and other viral infections, such as Influenza A, in order to limit viral RNA replication." (PMID 39670741, 2025). "Meanwhile, the transcriptional levels of interferon-stimulated genes (ISGs) such as ISG15, ISG20, OAS1, OAS2, MX1, and MX2 were significantly up-regulated, and these ISGs play a crucial role in resisting viral infection." (PMID 41153955, 2025). "The activation of the interferon response was further validated by the upregulation of MX1 and IFIT1, both have shown in prior virology studies to restrict viral replication, thereby reinforcing the relevance of the model to house viral infections." (PMID 41050093, 2025). "Based on interaction analysis, miR-324-3p mainly regulated FOSB, MX1, and IFIH1, which can inhibit transcription and replication in the early stages of viral infection, and stimulate to produce the innate immune response." (PMID 38178220, 2024). "The qRT-PCR results indicated an up-regulation trend for DDX58, STAT1, and MX1, while IRAK1, MAPK11, RELA, and ICAM1 exhibited a down-regulation trend as the duration of the viral infection increased." (PMID 38673764, 2024). "Mx1, a GTPase, is an ISG which plays a vital role in reducing influenza A and other viral infections in mice." (PMID 39224597, 2024). "The induction of OAS1, OAS2, and OASL, which, as main sensors for viral infections, explains the induction of numerous interferon-induced proteins (e.g., IFIT1, IFIT2, IFI44, MX1, MX2)." (PMID 39062793, 2024).
viral infection (continued). "Mx1 (MxA in humans) is established as an ISG that only reacts to IFN, but not directly to infection, whereas OAS1 can be induced by both virus infection and IFN." (PMID 37728614, 2023). "These pathways are closely related to the ability to respond to viral infections, and many downstream genes of JAK/STAT1/2-ISGs signaling, including Oas2, Ifit1, and MX1, which have anti-viral activities." (PMID 36599833, 2023). "In the current report, we found that IAV infection increases MAGI1 expression and enhances virus infection by inhibiting various anti-viral responses including STATs and IRF3 activation and induction of MX1 and OAS2." (PMID 36082118, 2022). "Downregulation of lincRNA‐EPS during viral infection or genetic knockout of lincRNA‐EPS facilitates PKR‐STAT1 signaling axis induced antiviral genes expression, such as Mx1, Oas2, Ifit2, and Irf7." (PMID 35312140, 2022). "It has been reported that interferon can significantly trigger the production of many interferon-induced genes (IFIT1, IFITM3, MX-1, OASL, ISG15, PKR, GBP1, Viperin, BST2, IRF-1, and CXCL10), which play key roles in the resistance to viral infection." (PMID 36337195, 2022). "In our data, the enriched pathways were related to viral infections such as influenza A (MX1, OAS1, OAS2, OAS3, RSAD2, STAT1) and measles (MX1, OAS1, OAS2, OAS3, STAT1)." (PMID 35464437, 2022). "IRF7, a crucial transcription factor to trigger innate immune responses, and Mx1, an important IFN-stimulated gene (ISG), play a pivotal role against viral infection." (PMID 35392111, 2022). "We validated the relevance of MX1, MX2, ISG15, and OAS1 in the context of viral infections in cell cultures in vitro and in a pre-clinical model of Coronavirus infection." (PMID 36298734, 2022). "ISGs products, including OAS1, OAS2, MX1, ADAR, and EIF2AK2, are major players in innate immune defence against viral infection." (PMID 36016774, 2022). "We identified that TGFβ suppressed IFNB1 expression as well as the interferon inducible genes, MX1 and viperin, consistent with the potential for TGF-β to suppress the innate immune response to viral infection." (PMID 35977489, 2022). "Subsequently, we visualized how those terms were linked to one another, which showed that for the horse there was a strong connection between liver pathology and viral infection, most likely driven by the activation of ISGs such as OAS1, MX1, and ISG20." (PMID 35527255, 2022). "IRF1 transcriptionally induced by the phosphorylated STAT1 and stabilized by XAF1 further facilitates the induction of the IRF1 target genes such as DDX58, DDX60, MX1, and OAS2 during viral infection." (PMID 35972291, 2022). "Genetic studies in mice have determined a specific role for each of the ISGs, including the antiviral myxovirus resistance protein 1 (MX1), the interferon-inducing transmembrane protein (IFITM), and PKR, in limiting virus infection and its spread." (PMID 33671828, 2021). "Mx1 is an effector ISG with GTPase activity and an antiviral effect against several viral infections, including influenza, bunyaviruses, and hantaviruses." (PMID 34372519, 2021). "The different consequences of PKR on Mx1, ISG15, and CCL5 expression kinetics suggest that, although all these genes are overall upregulated upon viral infections, they are also differently tuned by additional host factors such as PKR." (PMID 34372519, 2021). "ISG15, IRF7, MX1, RSAD2, and IFIT3 have been found to play a vital role in modulating immune response against the viral infection." (PMID 34631844, 2021). "Pre-treatment with L. gasseri SBT2055 induced the expression of antiviral genes Mx1 and 2′-5′ oligoadenylate synthase (OAS)1a in lung tissues before viral infection and reduced lung inflammatory responses after viral infection." (PMID 33081138, 2020). "ISGs are effector molecules that mediate cellular innate immune responses to viral infections, including PKR, OAS1, Mx1, and Mx2." (PMID 32133381, 2020).
viral infection (continued). "We cloned chicken MX1, IFI6, IFIT5, RSAD2, and OASL into eukaryotic expression vector and evaluated their effects on virus infection in DF1 cells." (PMID 32183248, 2020). "Mx1 is induced by the activation of type I and type III interferon signaling pathways, and serves as an intracellular restriction factor against viral infection such as influenza." (PMID 30696001, 2019). "We extended our analysis to a range of ISGs that have previously been identified as being regulated directly by virus infection in an IFN-independent manner i.e., IFIT1, IFIT2, IFIT3, ISG15, CXCL10, Mx1 and Mx2." (PMID 30871003, 2019). "Confirming our initial findings, viral infection of PVG rats increased the expression of Th1 and type I IFN target genes (MX1, ISG15, IRF7, and CXCL10)." (PMID 30150981, 2018). "Interferon signalling is essential for the production of anti-viral mediators (such as OAS1, Mx1, SP100, and TRIM22) to defend against virus infection." (PMID 28273165, 2017). "Because MX1 is one of the most important interferon-inducible anti-viral genes, we have not only identified a new diagnostic autoantibody of INSIP but also obtained new insight into the pathology of INSIP, which may be associated with viral infection and autoimmunity." (PMID 28230086, 2017). "It is well known that Mx1, OAS1, and PKR are potent antiviral effectors involved in the inhibition of viral infection." (PMID 28878774, 2017). "The RIG-I-MAVS pathway, through the production of type I IFN and subsequent production of ISGs such as Mx1, PKR, ISG15, RNase L, etc., restricts viral infection in various cellular compartments of the lungs." (PMID 27438481, 2016). "Lower-level IFN-β induction was accompanied by the downregulation of the MDA-5 and PKR genes and much weaker Mx1 and 2′,5′-OAS gene responses at 24 h p.i. than with the corresponding LPAI H2N3 virus infection." (PMID 25540384, 2015). "MX1 and OAS2 are antiviral proteins that play an important role in the type I interferon-mediated response against a broad range of viral infections." (PMID 26419927, 2015). "After viral infection, KIOM-C-treated RAW264.7 cells induced the antiviral (PKR, OAS, Mx-1), IFN-β and IFN-stimulated genes (ISG-15 and ISG-56) both at 12 and 24 hpi." (PMID 25942440, 2015). "Among these, the expression of Mx1, Mx2, TRIM22, WARS, ISG15, ISG20, UBA7, DDX58, and OAS1-3 were up-regulated, representing an increased innate immune response against viral infections." (PMID 25883591, 2015). "Pre-treatment with IFN-α14 highly induced the expression of ISGs such as MX1, OAS1, and PKR and upon virus infection, it efficiently suppressed viral replication compared with the other subtypes of IFN-α." (PMID 26694447, 2015). "In this study, we produced transgenic pigs over-expressing the Mx1 gene using the SCNT technology and explored its potency to protect porcine cells from viral infection." (PMID 25408889, 2014). "In particular, interferon stimulated pathways such as those including RSAD2, IRF7, MX1, OAS3, MDA-5, RIG-I and others are incorporated and thought to drive both innate and, to a lesser degree, adaptive immune responses to viral infection." (PMID 23326326, 2013). "The antiviral-ISG, including GBP1, IFI44, IFIH1, IFIT1, MX1, and LY6E, were the most common group of up-regulated genes after influenza infection, yellow fever vaccination, and during febrile episodes of dengue hemorrhagic fever." (PMID 24069471, 2013). "Specifically, we analyzed the effect of AdNrf2 alone or Nrf2 overexpression followed by infection with PR8 virus on the interferon-induced Mx1 and the OAS1 genes, which are involved in the innate immune response to viral infection." (PMID 22672594, 2012). "Our data revealed that, in RTG-2 cells, poly I∶C treatment before viral infection induced high levels of IFN1 and Mx1 and limited production of both wild-type and NV-knockout rIHNV." (PMID 21814578, 2011).
viral infection (continued). "The interferon-stimulated genes (ISGs), ISG15 and MX Dynamin-Like GTPase 1 (MX1), were also elevated at 3 dpi, indicating that airway tissue explants are not only infectable but can also respond to viral infection by activating interferon-mediated host innate defense pathways." (PMID 40279421, 2025). "Given the role of IFN signaling in mediating viral infection, uncontrolled peripheral viremia in nVS PWH may have a greater impact on the level of Mx1-expressing cells in the brain than local viral persistence alone, particularly in myeloid cells in nVS PWH." (PMID 40469287, 2025). "It is worth noting that genes relating to innate immune response to viral infection (e.g., DHX58, MX1, IFITM-like), cell structure integrity (e.g., ANGPTL3, ANGPTL4, ELFN2, COL5A3) and transcription factors (e.g., TUB) remained upregulated throughout the acute phase of infection (1–6 dpi)." (PMID 40758745, 2025). "Epithelial cells produce MX-1 as part of their innate defense mechanism against viral infections at the point of entry, while macrophages do not activate this mechanism." (PMID 41012169, 2025). "While not as well studied as MX1, IFIT1 encodes for a family of IFN-induced proteins with tetratricopeptide repeats that are induced after viral infection or PAMP recognition." (PMID 38932231, 2024). "This enrichment may be attributed to the increased expression of ISGs like MX1 and RSAD2 during the early stages of the viral infection, leading to a higher demand for enzymes and energy production in organelles such as mitochondria." (PMID 38673764, 2024). "During virus infection, viral RNA activates host PRRs to trigger the signal pathway of type I IFNs, which induce the expressions of ISGs to result in the production of a series of antiviral proteins (such as OAS and Mx1), and thus produce the antiviral effect." (PMID 36960283, 2023). "We speculate that IFI27, BST2, MX1 and ISG15 may play an important role in the suppression of ZIKV and other viral infections rendered by NS4A." (PMID 35522620, 2022). "In the present study, the transcription levels of IFN-β, OAS1, Mx1, and ISG15 in the lungs and intestines of mice pretreated with L. plantarum 0111 were correspondingly increased, and the lung viral load was significantly reduced after viral infection." (PMID 35847111, 2022). "More importantly, blockage of the cleavage (D126A) significantly increased the IFN-β promoter activity, mRNA levels of IFN-β and ISGs (IFIT-1 and MX1), and IFN-β production in the supernatants, especially at the late stage of virus infection and poly(I·C) treatment." (PMID 34125604, 2021). "Moreover, IFN-β stimulates the expression of ISGs including IFN-induced transmembrane protein 1 (IFITM), Mx1, protein kinase R (PKR), and OAS, which function as effectors in the cellular response to virus infection." (PMID 34696478, 2021). "In humans, MX1 and MX2 (also known as MxA and MxB respectively) are, in contrast to many other interferon-induced proteins, strictly induced by IFN and found to be increased in the plasma of patients suffering from viral infections." (PMID 34079538, 2021). "In light of our observation that the induction of MX1 transcripts after ZIKV infection was not only RIG-I, but also partially MDA5-dependent, we wanted to further investigate how the individual receptors influence transcriptomic changes after virus infection." (PMID 32560274, 2020). "Classical ISGs responsible for inhibition of viral infection include OAS1, MX1, and ISG15." (PMID 32760370, 2020). "In the upregulated genes in both chMDA5 and poly(I:C) groups, many genes were ISGs, such as MX1, IFI6, IFIT5, RSAD2, OASL, and, CMPK2, which suggested that these genes might play important roles in restricting virus infection in chicken." (PMID 32183248, 2020).
viral infection (continued). "Meanwhile, we found that IFNs could significantly trigger the production of a variety of IFN-induced genes (IFIT1, IFITM3, Mx-1, OASL, ISG15, PKR, GBP1, Viperin, BST2, IRF-1, and CXCL10) and MHC molecules, which play key roles in resistance to virus infection." (PMID 32655518, 2020). "The myxovirus resistance 1 (Mx1) gene is one of the most prominent interferon (IFN)-stimulated genes in vertebrate that are highly activated when triggered by type I and III IFNs upon viral infection." (PMID 26411585, 2015). "The expression of Mx1 is strongly induced by IFN-α/β,double-stranded RNA or viral infections." (PMID 25408889, 2014). "Despite the potent antiviral activity of Mx1, its utility to protect large animals, such as pigs, from viral infection has not yet been explored." (PMID 25408889, 2014). "The majority of the top 50 predictive genes contained in each factor are known to characterize host response to viral infection, and include RSAD2, the OAS family, multiple interferon response elements, the myxovirus-resistance gene MX1, cytokine response pathways and others." (PMID 23326326, 2013). "This Hypothesis is supported by the upregulation of MX1 and MX2, both of which are up-regulated in response to viral infection." (PMID 20707927, 2010). "MX1, MX2, and OAS family members OAS1, OAS2, OAS3 mediate resistance to virus infection." (PMID 18648529, 2008). "Host cells sense viral infections through various pattern recognition receptors (PRRs) and initiate innate immune responses, especially activation of the IFN response to produce a variety of antiviral proteins such as RSAD2 and Mx1 to fight against viral infections." (PMID 38257818, 2024). "Expression of two antiviral proteins was measured from which we expected different expression patterns: MX1, a protein rapidly induced by type‐I interferon which is interfering with viral replication, as well as IFI44L, recently shown to negatively regulate cellular responses after virus infections." (PMID 34169553, 2022). "Previous research showed that myxovirus (influenza virus) resistance 1 (MX1) and ISG15 were up-regulated in the PBMCs from PI cattle which infected with BVDV-1, suggesting that the CP and NCP BVDV could lead the production of ISGs to resist viral infection." (PMID 34872498, 2021). "Porcine Mx1 overexpression has been shown to exert an inhibitory effect on FMDV and bovine viral diarrhea virus (BVDV) replication within 12 and 36 h post-infection, and protection against viral infection in cells of transgenic pigs expressing the Mx1 transgene has also been reported." (PMID 26193305, 2015). "The increased expression of dsRNA receptor TLR3 and IFN induced genes ISG56, ISG43, Mx1 and IFIT3 after stimulation with poly I:C mimicking a viral infection indicates that these cell lines can be used as effective in vitro models to study the bat's innate immune responses to virus infection." (PMID 25295526, 2014). "In addition, this mutant failed to block the inductions of IFN1 and Mx1 in RTG-2 cells treated with poly I∶C after viral infection." (PMID 21814578, 2011). "Additionally, alternative splicing of MX1 supports rather than restricts viral infection." (PMID 37497545, 2023). "Importantly, the feIFN-ω’ can effectively promote the expression of antiviral proteins IFIT3, ISG15, Mx1, and ISG56, and further enhance host defense to eliminate FPV infection in vivo, suggesting a potential candidate for the development of therapeutic agent against feline viral diseases." (PMID 35068319, 2022). "We focused on MX1 because it achieved the highest single gene point estimate AUROC for discriminating groups of individuals with and without replicative viral infection at the first time point at which any biomarker achieved significant discrimination." (PMID 39616162, 2024).